JAM3 (junctional adhesion molecule 3)
Diseases named in the same sentence as JAM3 in open-access papers (continued):
Sharing a sentence is not in itself a finding about the gene and the disease.
ovarian carcinoma (4 papers, 2013 to 2025). A malignant neoplasm originating from the surface ovarian epithelium. "miR-127 has been reported as a tumor-suppressor and a potential diagnostic biomarker for multiple cancers, while JAM3 has been reported to promote tumor growth and aggressiveness of ovarian cancer." (PMID 32979257, 2020). "CircKIF4A knockdown suppresses ovarian cancer cell proliferation as well as migration, and as a kind of ceRNA, circKIF4A can upregulate JAM3 levels via sponge adsorption of miR-127 to enhance ovarian cancer progression." (PMID 35579738, 2022). "Here, we found that circKIF4A sponged miR-127 and up-regulate the expression of JAM3 to promote ovarian cancer progression." (PMID 32979257, 2020). "Subsequent mechanism study revealed that circKIF4A acted as a competitive endogenous RNA (ceRNA) to promoted ovarian cancer progression by sponging miR-127 and upregulated the expression of Junctional adhesion molecule 3 (JAM3)." (PMID 32979257, 2020). "Subsequent mechanism study revealed that circKIF4A promoted ovarian cancer progression by sponging miR-127 and upregulated the expression of Junctional adhesion molecule 3 (JAM3)." (PMID 32979257, 2020). "In ovarian cancer, JAM3 promotes tumor growth and aggressiveness." (PMID 32979257, 2020).
liver fibrosis (3 papers, 2019 to 2022). "Moreover, the upregulation of JAM2 and JAM3 by endothelial cells and de novo synthesis of JAM3 by hepatic stellate cells trigger autoimmune-mediated liver fibrosis in mice." (PMID 32932992, 2020).
myeloma (3 papers, 2014 to 2024). "These include adhesion molecules such as JAM2 and JAM3 as well as CR2, the latter of which was shown to play a role in the interaction of myeloma cells with the bone marrow stroma." (PMID 25188243, 2014).
bladder cancer (2 papers, 2024). "Finally, JAM3 is negatively associated with CD8+ cell infiltration in bladder cancer samples, while integrins significantly correlate with immune cell infiltration in skin cutaneous melanoma, bringing our discussion back to antineoplastic immunity, the leitmotif of these results." (PMID 39202425, 2024).
brain hemorrhages (2 papers, 2022 to 2023). "Disruptions of the genes, such as the COL4A1 and COL4A2 genes, are common genetic causes identified in fetal intracranial hemorrhage; however, the disruptions of the JAM3 gene are rarely reported." (PMID 36339007, 2022). "Our findings expanded the spectrum of the pathogenic mutations in the JAM3 gene and revealed an important application of fetal whole-exome sequencing in idiopathic fetal intracranial hemorrhage." (PMID 36339007, 2022).
glioma (2 papers, 2015 to 2020). A benign or malignant brain and spinal cord tumor that arises from glial cells (astrocytes, oligodendrocytes, ependymal cells). "Blocking JAM2 and JAM3 in vitro impaired the growth and invasion of glioma cells, and their expression was increased in tumor cells." (PMID 25879740, 2015).
Immunodeficiency (2 papers, 2019 to 2021). Failure of the immune system to protect the body adequately from infection, due to the absence or insufficiency of some component process or substance. "The deletion of the FLI-1, ETS1, JAM3 and THYN1 genes was considered to be directly associated with the immunodeficiency exhibited by the patient." (PMID 34440371, 2021). "Besides, the expression of JAM3 is decreased in this progression and its defection may cause immunodeficiency in mice, which in turn reduces tumor immune surveillance; in the second pathway, homeobox protein NKX2-5 upregulates target genes PAP2C and JMY, which can lead to cancer cell apoptosis." (PMID 31126066, 2019). "The expression of the THYN1 gene in these immune cells leads us to propose its implication in the immunodeficiency of JBS patients, along with FLI-1, ETS1, NFRKB and JAM3." (PMID 34440371, 2021). "ETS1, NFRKB, JAM3 and THYN1 genes could also play a role in the presence of immunodeficiency." (PMID 34440371, 2021).
infertile (2 papers, 2015 to 2021). "The initial studies in vivo using Jam3 KO mice showed that the deletion of Jam3 is to a large extent lethal, but the remaining male mice were infertile mice." (PMID 34395412, 2021).
male infertility (2 papers, 2012 to 2017). The inability of the male to effect fertilization of an ovum after a specified period of unprotected intercourse. "Gorasp2-/- mice display male infertility but do not present other gross morphological defects, similarly to Jam3-deficient mice." (PMID 28617811, 2017).
meningioma (2 papers, 2024 to 2026). A generally slow growing tumor attached to the dura mater. "The results of this study provide valuable insight into the mechanisms of meningioma formation and ferroptosis, suggesting that miR-127–5p plays a critical regulatory role through interaction with JAM3." (PMID 38577017, 2024). "MiR-127–5p was found to be expressed at low levels, whereas JAM3 was expressed at high levels in meningioma cells." (PMID 38577017, 2024).
microcephaly (2 papers, 2023 to 2025). A congenital or acquired developmental disorder in which the circumference of the head is smaller than normal for the person's age and sex. "JAM3 causes AR Porencephaly-microcephaly-bilateral congenital cataract syndrome (HDBSCC, MIM #613730), in which extensive hemorrhage appears to be the main event causing the FBDS." (PMID 40143324, 2025).
ZIKV infection (2 papers, 2019 to 2025). "The in vitro data fully corroborated with animal experiments in which we observed that ZIKV infection downregulated the expression of claudin-5, occludin, JAM-3, and ZO-1 protein levels in Bmal1ECKO mice." (PMID 40313764, 2025). "ZIKV infection resulted in a marked decrease in claudin-5, occludin, JAM-3, and ZO-1 expression levels in these mice." (PMID 40313764, 2025). "Importantly, ZIKV infection in Bmal1ECKO mice resulted in a significant decrease in the expression of claudin-5, occludin, JAM-3, and ZO-1 proteins when compared to controls." (PMID 40313764, 2025). "In the next series of experiments, we focused on the impact of ZIKV infection and/or Bmal1 silencing on the expression of TJ genes and proteins, such as claudin-5, occludin, zona occludens (ZO-1), and junctional adhesion molecule-3 (JAM-3)." (PMID 40313764, 2025).
asthma (1 paper, 2021). "Similarly, JAM3 expression was downregulated in the asthmatic/asthmatic group compared with control/control one, further supporting a role in asthma." (PMID 35387054, 2021).
auditory neuropathy (1 paper, 2023). A hearing disorder characterized by impaired transmission of signals through the auditory nerve, resulting in mild to severe hearing loss and poor speech perception. "Thin CC, cortical dysgenesis, and auditory neuropathy could be explained by the important role of JAM3 in Schwann cells, myelin sheath, and neural migration." (PMID 37780041, 2023).
bipolar disorder (1 paper, 2015). A disorder of the brain that causes unusual shifts in mood, energy, activity levels and the ability to carry out day-to-day tasks. "The result showed that 6 genes (including MAD1L1, JAM3, MYL12B, MYL12A, ITIH1 and RYR2) had been reported to be significant associated with bipolar disorder in at least one genetic study." (PMID 26193471, 2015).
cerebral cavernous malformation (1 paper, 2022). A disorder characterized by malformations in the structure of the capillaries in the brain. "Interestingly, gene mutations in endothelial junctional proteins occludin, junctional adhesion molecule 3 (JAM3) and cerebral cavernous malformation (CCM) −1, −2, −3 lead to the BBB deficiency and brain calcification." (PMID 35309892, 2022).
cervical disease (1 paper, 2026). "The PAX1/JAM3 methylation panel could serve as a triage tool for CC among women undergoing evaluation for cervical disease, particularly in postmenopausal patients and may enhance colposcopy by providing more accurate lesion diagnosis." (PMID 41239544, 2026).
cervical tumors (1 paper, 2025). "Furthermore, marker performance varies by histology: PAX1 is more sensitive for squamous cell carcinoma, while JAM3 better detects adenocarcinoma and rare cervical tumors." (PMID 41358249, 2025).
cholangiocarcinoma (1 paper, 2024). A carcinoma that arises from the intrahepatic biliary tree (intrahepatic cholangiocarcinoma) or from the junction, or adjacent to the junction, of the right and left hepatic ducts (hilar cholangiocarcinoma). "Junctional adhesion molecular 3 (JAM3) is downregulated by hypermethylation in cancers but is unclear in cholangiocarcinoma." (PMID 38124399, 2024). "The expression of JAM3 mRNA in three cholangiocarcinoma cell lines, including RBE, HCCC‐9810 and HuCCT1 cells, was detected using RT‐PCR." (PMID 38124399, 2024). "Methylated JAM3 DNA may represent a non‐invasive molecular marker for the early detection of cholangiocarcinoma and prognosis." (PMID 38124399, 2024). "The roles of JAM3 in cholangiocarcinoma were studied by transfection of siRNA and pCMV3‐JAM3." (PMID 38124399, 2024). "The JAM3 expression level was checked in cholangiocarcinoma cell lines and tissues." (PMID 38124399, 2024).
chronic rhinosinusitis (1 paper, 2022). Chronic form of sinusitis. "Nevertheless, JAM3 mRNA expression was downregulated in chronic rhinosinusitis patients with nasal polyps versus healthy controls." (PMID 35372516, 2022).
coronary disease (1 paper, 2009). "Polymorphisms in the SNX19 gene have been proposed to be associated with coronary disease and the JAM3 gene has previously been proposed as a candidate gene for the JBS cardiac phenotype." (PMID 20003197, 2009).
demyelination (1 paper, 2022). "Therefore, the downregulation of Jam3 could contribute to the loss of myelin integrity that occurs in cuprizone-induced demyelination." (PMID 36499195, 2022).
dilatation (1 paper, 2017). "MRI displayed multifocal intra-parenchymal haemorrhages in the white matter and basal ganglia with secondary ventricular dilatation owing to major JAM3 expression in the vascular endothelium." (PMID 28460636, 2017).
epilepsy (1 paper, 2021). A brain disorder characterized by episodes of abnormally increased neuronal discharge resulting in transient episodes of sensory or motor neurological dysfunction, or psychic dysfunction. "We observed a reduction of Cstb, Jam3, Zc3h14, and Msn, which can cause neuroinflammation and epilepsy (Cstb), blood-brain-barrier disruption (Jam3), impairment of synaptic function (Zc3h14) and long-term memory (Msn)." (PMID 35155612, 2021).
gastric adenocarcinoma (1 paper, 2015). "Overexpression of JAM3 in an epithelial carcinoma cell line improved tight junctions and restored an epithelial phenotype, and the expression was downregulated in gastric adenocarcinoma tissue." (PMID 26517242, 2015).
gastric cancer (1 paper, 2023). A primary or metastatic malignant neoplasm involving the stomach. "However, the potential prognostic role of JAM3 in gastric cancer (GC) remains unclear." (PMID 37115068, 2023).
ischemic stroke (1 paper, 2024). A stroke disorder caused by obstruction of blood flow to the brain, due to thrombotic (local blood clot formation) or embolic (due to a blood clot or other material traveling from another site) event. "In the adult brain, TJAP-1 and JAM3 (alias JAM-C) are important for blood–brain barrier integrity and were identified as potential therapeutic targets of the protective microRNA-132/212 after ischemic stroke." (PMID 38338705, 2024).
joint disease (1 paper, 2019). "Biological inference prioritized notable DMRs associated with skin disease (SIGLEC14, JAM3, PCOLCE, RXRB), skin and/or joint disease (MBP, OSBPL5, SNORD115, HCG26), and joint disease (IL22, ELF5, PPP2R2D, PTPRN2, HCG26)." (PMID 30779748, 2019). "Although few DMRs exceeded a 10% change in methylation, it is noteworthy that many of those which did play roles in the pathogenesis of skin disease (SIGLEC14, JAM3, PCOLCE, RXRB, ELF5, IL22), joint disease (MBP, HCG26, IL22, PPP2R2D, PTPRN2) or are known to be imprinted (OSBPL5, SNORD115)." (PMID 30779748, 2019).
metastatic tumors (1 paper, 2023). "Interestingly, we discovered through systematic screening for metastasis-associated DNA methylation changes mechanisms leading to downregulation of JAM3 expression in metastatic tumors, namely DNA hypomethylation at a distal ESR1 binding site and DNA hypermethylation of the gene promoter." (PMID 36585450, 2023).
Obesity (1 paper, 2022). Accumulation of substantial excess body fat. "Cell junction proteins showed enriched expression in fenestrated ECs, and Jam3, Pdch12, Afdn and Tjp1 were upregulated in obesity in fenestrated ECs." (PMID 36400935, 2022).
primary ciliary dyskinesia (1 paper, 2021). A rare, genetically heterogeneous, primarily respiratory disorder characterized by chronic upper and lower respiratory tract disease. "This could be considered as the first connection between Jam3 and cilium, taking into account that frequently mutations that generate motile cilia defects, like those found in primary ciliary dyskinesia (PCD), also have an effect on sperm tail formation." (PMID 34395412, 2021).
renal cell carcinoma (1 paper, 2022). "The study performed on renal cell carcinoma showed that the JAM3 gene is critical for its tumor migration ability via the regulation of genes coding for N-cadherin, integrin β1 (ITGB1) and MMP2." (PMID 35742950, 2022).
Respiratory tract infection (1 paper, 2021). An infection of the upper or lower respiratory tract. "The Jam3 expression pattern in the airway is completely unknown, even though mice lacking the Jam3 gene die due to respiratory tract infections." (PMID 34395412, 2021).
type 1 diabetic (1 paper, 2020). "In type 1 diabetic mice, JAM2 and JAM3 have been reported to polarize leukocyte trans-endothelial migration and subsequently destruct insulin-producing beta cells in the pancreas." (PMID 32932992, 2020).
viral infection (1 paper, 2019). "Some proximal genes targeted by these 6 REs (FSCN1, GSTP1, JAM3, CHRNA6, NFAT5, and PRRC2A) are related to immune response, viral infection, and/or HCC based on ontological analysis." (PMID 31639042, 2019).
tumor (37 papers, 2011 to 2025). "Methylation of JAM3 was also found to be associated with tumour differentiation, metastasis and TNM stage, while transfection of JAM3 induced apoptosis and repressed CCA cell viability, invasion and migration." (PMID 38124399, 2024). "Methylation of JAM3 was associated with tumour differentiation (p = 0.011), metastasis (p = 0.035) and TNM stage (p < 0.001)." (PMID 38124399, 2024). "JAM3 was methylated in 26.5% (13/49) of EIN and 51.1% (388/760) of primary EC, and methylation of JAM3 was associated significantly with tumor differentiation and family history (all p < 0.05)." (PMID 36461092, 2022). "Reduced JAM3 expression is associated with enhanced tumor cell viability and migration." (PMID 39781359, 2025). "Hypermethylation of JAM3 was associated with tumour differentiation, metastasis and TNM stage." (PMID 38124399, 2024). "Methylation of JAM3 was associated significantly with tumor differentiation and family history." (PMID 36461092, 2022). "Re-expression of JAM3 through demethylation strategies results in the suppression of tumor cell growth and migration." (PMID 39781359, 2025). "Using the CIBERSORT algorithm, we investigated the connection between JAM3 and tumor immunity by calculating the infiltration of 22 different immune cell types in each BC sample." (PMID 38400838, 2024). "This also refers to the next study direction: in BC, JAM3 promotes tumor growth via the PI3K-AKT pathway, including proliferation, migration, and invasion." (PMID 38400838, 2024). "In CRC, JAM3 has been reported as a tumor suppressor gene and plays a crucial role in the growth and migration of tumor cells." (PMID 38872418, 2024). "Specifically, we looked into how JAM3 expression relates to immune cell infiltration in the GC tumor microenvironment." (PMID 37115068, 2023). "Recent research has shed light on the crucial role of JAM3 in the regulation of tumor growth during tumor progression." (PMID 37671063, 2023). "JAM3, LIF, CD38, and SIGGIR, upregulated in our study, exert angiogenic and tumor-promoting effects and are linked to unfavorable cancer prognosis." (PMID 37762335, 2023). "Our findings expand what is known about JAM3 possible function in the tumor immunology of GC and its prognostic importance." (PMID 37115068, 2023). "Further study demonstrated that JAM3 suppressed EC cells and xenograft tumor growth by inhibiting Wnt/β-catenin signaling." (PMID 36461092, 2022). "The tumor volume was 514.83 ± 55.08mm3 and 59.93 ± 24.28mm3 in JAM3 unexpressed and re-expressed KYSE410 cells xenografts." (PMID 36461092, 2022). "The tumor volume was significantly smaller in JAM3 re-expressed KYSE410 cell xenografts than in JAM3 unexpressed KYSE410 cell xenografts (p < 0.001)." (PMID 36461092, 2022). "Cell-cell and cell-matrix adhesion genes such as Jam3 or integrin αIIb were differentially regulated in the tumor-draining lymph node, suggesting that LECs in tumor-draining lymph nodes are altered at a transcriptional level." (PMID 33330052, 2020). "For instance, expression of Jam3, the gene-encoding junctional adhesion molecule C (JAM-C), was significantly reduced in both tumor models." (PMID 30590031, 2018). "Junctional adhesion Molecule-C (JAM-3) involved in cell adhesion and associated with tumor growth was identified down-regulated in T24MshPFN1 (0.64-fold) vs T24MshSCR cells." (PMID 27683119, 2016). "In our study, we observed a negative correlation (R ═ −0.12) between tumor mutation burden and JAM3 expression." (PMID 38400838, 2024). "Our data suggest that JAM3 serves as a tumour suppressor in CCA." (PMID 38124399, 2024). "In addition, JAM3 was associated with the CD200, an inhibitory immune checkpoint that suppressed anti-tumor immune function by binding its receptor CD200R on myeloid cells." (PMID 38400838, 2024). "Additionally, the possible relationship between JAM3 and immune infiltration levels in GC was evaluated using the Tumor Immune Estimation Resource (TIMER) database." (PMID 37115068, 2023).